SIGLEC15 (sialic acid binding Ig like lectin 15)
Diseases named in the same sentence as SIGLEC15 in open-access papers (continued):
Sharing a sentence is not in itself a finding about the gene and the disease.
lung adenocarcinoma (6 papers, 2021 to 2025). A carcinoma that arises from the lung and is characterized by the presence of malignant glandular epithelial cells. "Elevated levels of SIGLEC-15 correlate with poor prognosis in various malignancies, including lung adenocarcinoma, pancreatic cancer, and colorectal cancer, suggesting its involvement in tumor progression and immunosuppression." (PMID 40943560, 2025). "It was found that an anti-Siglec15 antibody enhanced the treatment of lung adenocarcinoma with increased destruction of tumor cells, possibly due to macrophage polarization affecting the TME." (PMID 38919533, 2024). "In addition, some researchers have used the Siglec15 protein to determine the therapeutic effects against lung adenocarcinoma in nude mice." (PMID 38919533, 2024). "Interestingly, studies have shown that the expression of SIGLEC-15 and PD-L1 can be mutually exclusive in certain tumors, including lung adenocarcinoma and bladder cancer, indicating that these markers might serve different immunosuppressive mechanisms." (PMID 40943560, 2025). "However, the association between Siglec‐15 expression and clinicopathological features of lung adenocarcinoma (LUAD), especially the prognostic role, is not fully elucidated." (PMID 38725348, 2024). "Both in vitro and in vivo, cMet/Siglec15 CAR-T cells showed obvious cytotoxicity against lung adenocarcinoma cells, and at the same time, they could significantly inhibit the growth of lung adenocarcinoma cells in situ and increase the infiltration of T cells in the TME." (PMID 38919533, 2024).
colorectal cancer (5 papers, 2010 to 2023). A primary or metastatic malignant neoplasm that affects the colon or rectum. "SIGLEC15 is expressed in tumor cells, and anti-SIGLEC15 mAb inhibitors can significantly upregulate the immunosuppressive function of colorectal cancer in mice." (PMID 37207210, 2023). "Particularly, we showed that SIGLEC15 is a key immune suppressor in the pre-metastatic lymph node, which might be a critical factor in the lymph node metastasis of colorectal cancer." (PMID 34722496, 2021). "The data showed that the relative expression of SIGLEC15 was increased in the MSS group compared with the MSI-H group, suggesting that SIGLEC15 may reflect immunological characteristics of colorectal cancer." (PMID 34722496, 2021). "Furthermore, the relationship between SIGLEC15,TIGIT,LAG3,CTLA4, PDCD1LG2 immune checkpoints and Mapk14 was only verified by correlation analysis, and we need to further explore the mechanism of Mapk14 expression in colorectal cancer in vitro and vivo experiments, such as single cell RNA sequencing." (PMID 35141222, 2022).
lung carcinoma (4 papers, 2023 to 2025). "cMet/Siglec15 CAR-T cells demonstrated clear cytotoxicity against lung cancer cells, both in vitro and in vivo." (PMID 40981188, 2025). "Some researchers have employed the Siglec15 protein to test its therapeutic efficacy against lung cancer in nude mice." (PMID 40981188, 2025). "Wang and colleagues first reported this phenomenon in lung cancer, identifying SIGLEC-15 as a novel immune checkpoint molecule that is mutually exclusive with PD-L1 in tumor tissues." (PMID 40943560, 2025).
melanoma (4 papers, 2020 to 2023). A malignant, usually aggressive tumor composed of atypical, neoplastic melanocytes. "In addition, they found SIGLEC15 deficiency promoted T cell responses, better tumor control, and overall survival in a mouse melanoma model." (PMID 35480320, 2022). "A recent study concerning SIGLEC15 also showed expression of SIGLEC15 by macrophages or tumor cells could directly depress function of CD8+ T cells in a melanoma model." (PMID 33240817, 2020). "Former studies showed SIGLEC family genes were expressed on immune cells and were involved in immune cell activation and adaptation; also, recently, SIGLEC15 was found to be able to dampen CD8+ T cell infiltration and function in mouse melanoma model." (PMID 33240817, 2020). "Considering that CYTL1 may be a potential oncogene in melanoma, it was assessed how CYTL1 interacted with PDCD1, CD274, HAVCR2, TIGIT, SIGLEC15, CTLA4, LAG3, and PDCD1LG2." (PMID 37745303, 2023).
osteosarcoma (4 papers, 2022 to 2023). A usually aggressive malignant bone-forming mesenchymal neoplasm, predominantly affecting adolescents and young adults. "In MNNG/HOS and 143B osteosarcoma cells, the overexpression of SIGLEC-15 promotes the proliferation, migration, and invasion of tumor cells." (PMID 36358792, 2022). "In summary, our study reveals for the first time the prometastatic mechanism of Siglec15-induced autophagy in osteosarcoma." (PMID 35842729, 2022). "Our studies confirmed that Siglec15-induced autophagy could promote the invasion and migration of osteosarcoma cells." (PMID 35842729, 2022). "Jude PeCan database, among common pediatric cancers, we found higher SIGLEC15 expression in B-ALL, AML, mixed lineage leukemia, and osteosarcoma relative to the median expression across all tumors." (PMID 37465593, 2023). "GSEA conducted on all genes demonstrated that patients of S-I tended to exhibit more osteoclastic bone resorption (e.g., ACP5, SIGLEC15, CTSK), which was consistent with the clinical manifestations of osteosarcoma at the early stage." (PMID 36874110, 2023). "Similarly, in osteosarcoma, another signal of STAT3/Bcl-2 is also shown be involved in tumor proliferation, and the silencing of SIGLEC-15 induces the upregulation of apoptosis- and pyroptosis-related proteins." (PMID 36358792, 2022).
sarcoma (4 papers, 2020 to 2023). A usually aggressive malignant neoplasm of the soft tissue or bone. "By contrast, up-regulated SIGLEC15 expression was associated with shorter OS in kidney renal clear cell carcinoma, pancreatic adenocarcinoma and Sarcoma, and with shorter RFS in SARC and PAAD." (PMID 33796453, 2021). "Similarly, Siglec15 was also overexpression in immune desert tumor—sarcoma, and was involved in immune-related pathways and predicted poor prognosis." (PMID 37859817, 2023). "Also, SIGLEC11 mRNA expression was down-regulated in 19 out of 24 cancer types (except GBM, HNSC, THCA, and sarcoma [SARC], prostate adenocarcinoma [PRAD]), and SIGLEC15 was up-regulated in 18 out of 24 cancer types (except BRCA, KIRC, LUSC, PRAD, thymoma [THYM], and skin cutaneous melanoma [SKCM])." (PMID 33240817, 2020).
colon adenocarcinoma (3 papers, 2021 to 2023). "However, the significance of Siglec15 and its relationship with programmed death-ligand 1 (PD-L1) in colon adenocarcinoma (COAD) remain unknown." (PMID 37859817, 2023). "The relationship between Siglec15 and the immune microenvironment in colon adenocarcinoma (COAD), especially MMR-p COAD, has not been elucidated." (PMID 37859817, 2023).
colon carcinoma (3 papers, 2021 to 2023). "In fact, a previous study on colon carcinoma validated the essential function of Siglec15 expressed by TAMs." (PMID 37325664, 2023). "Siglec15 blocking mAbs significantly inhibited tumor growth in mice inoculated with colon carcinoma cells mixed with wild-type bone marrow-derived macrophages (BMDMs) but not with Siglec15 knockout BMDMs." (PMID 37325664, 2023). "Previous studies have indicated that patients with MMR-p COAD could not benefit from immunotherapy; therefore, we were curious regarding the role of Siglec15 and PD-L1 in MMR-p colon cancer." (PMID 37859817, 2023).
hepatocellular carcinoma (3 papers, 2023 to 2026). A malignant tumor that arises from hepatocytes. "Similarly, the LINC02432/hsa-miR-98–5p/HK2 axis also correlated with SIGLEC15 regulation in hepatocellular carcinomas (HCC)." (PMID 37869015, 2023).
pancreatic ductal adenocarcinoma (3 papers, 2022 to 2023). An infiltrating adenocarcinoma that arises from the epithelial cells of the pancreas. "In pancreatic ductal adenocarcinoma, SIGLEC15 has been identified as a tumor-associated macrophage-associated immune checkpoint that polarizes M2-type macrophages and promotes tumor growth." (PMID 37424730, 2023). "Several studies displayed the complicated function of SIGLEC15 and validated that SIGLEC15 could act as a potential immunotherapeutic target for pancreatic ductal adenocarcinoma." (PMID 36159823, 2022).
non-small cell lung carcinoma (2 papers, 2021 to 2022). A group of at least three distinct histological types of lung cancer, including non-small cell squamous cell carcinoma, adenocarcinoma, and large cell carcinoma. "The results of a phase I clinical trial in advanced non-small cell lung cancer (NSCLC) indicated that Siglec15 inhibitors achieved a promising clinical response (NCT03665285)." (PMID 33537076, 2021). "In addition, the pan-cancer analysis and our result showed that the expression of SIGLEC15 may play distinctive roles in different human cancers, such as acting as an immunosuppressor in “hot tumor” non-small cell lung cancer, so anti-SIGLEC15 therapy was suitable for such tumor." (PMID 36159823, 2022).
osteopetrosis (2 papers, 2020 to 2023). Osteopetrosis, also known as marble bone disease, is a descriptive term that refers to a group of rare, heritable disorders of the skeleton characterized by increased bone density on radiographs. "Takahata’s group, using another line of Siglec15 null mice, demonstrated that their null mice also show mild osteopetrosis in trabecular bones, confirming the findings by Hiruma’s group." (PMID 31900164, 2020). "Hiruma and colleagues reported that Siglec15 null mice showed mild osteopetrosis (increased bone mass) in trabecular bones (i.e., porous, spongy bones) and reduced urinary deoxypyridinoline (a systemic marker of bone resorption), indicating reduced osteoclast activity." (PMID 31900164, 2020).
ovarian carcinoma (2 papers, 2021 to 2023). A malignant neoplasm originating from the surface ovarian epithelium. "Nevertheless, the specific mechanism of SIGLEC15 in ovarian cancer requires further study." (PMID 37424730, 2023).
pancreatic cancer (2 papers, 2023). "Siglec15 is rising as a promising immunotherapeutic target in bladder, breast, gastric, and pancreatic cancers." (PMID 37325664, 2023). "Combining this with the observation of SIGLEC15’s mutually exclusive expression with B7-H1(PD-L1) suggests that SIGLEC15 levels may play a role in pancreatic cancer immune evasion." (PMID 38062391, 2023). "Moreover, SIGLEC15, rather than other immune checkpoint genes, was found to have a positive expression correlation with upregulated genes in pancreatic cancer." (PMID 38062391, 2023).
pulmonary tuberculosis (2 papers, 2020 to 2021). A bacterial infection that affects the lungs and is caused by Mycobacterium tuberculosis. "SIGLEC15 inhibits T cells proliferation and activation, and SNPs in this gene has been associated with Candida albicans infections and pulmonary tuberculosis." (PMID 34531865, 2021). "Another recent association study (involving 114 pairs of pulmonary tuberculosis patients and their asymptomatic household contacts in West Bengal, India) showed that another SIGLEC15 polymorphism (rs61104666 A, synonymous substitution at Glu292) is associated with pulmonary tuberculosis." (PMID 31900164, 2020).
rectum adenocarcinoma (2 papers, 2021 to 2023). An adenocarcinoma arising from the rectum. "Kaplan–Meier analysis showed that SIGLEC15 mRNA level has no significant influence in rectum adenocarcinoma (P = 0.27)." (PMID 34722496, 2021).
Sepsis (2 papers, 2021 to 2022). Sepsis is defined as life-threatening organ dysfunction caused by a dysregulated host response to infection. "Our analysis showed that multiple immune checkpoints (CD274 [coding PD-L1], HAVCR2 [coding TIM3], and SIGLEC15 [coding SIGLEC-15]) were also highly expressed in sepsis." (PMID 35844488, 2022). "Immune checkpoint-related genes CD274 (PD-L1), HAVCR2 (TIM3), and SIGLEC15 were overexpressed in sepsis." (PMID 35844488, 2022).
allergies (1 paper, 2020). "C2, C9, IL5, SIGLEC15, and IL1RAP are examples of molecules with roles in immunity, inflammation and allergy that demonstrate seasonal effects." (PMID 33004787, 2020). "SIGLEC15 and IL1RAP peak in late spring/early summer, consistent with their role in allergies which often peaks in spring and early summer, and IP10, C2 and C6 peak in late fall/winter consistent with their role in fighting infections which often occur during the late fall/winter." (PMID 33004787, 2020).
colorectal tumor (1 paper, 2026). "Interestingly, overexpression of the SIGLEC15 protein in colorectal tumor cells is associated with advanced TNM stage and predicts fewer tumor-infiltrating lymphocytes." (PMID 41158758, 2026).
glioblastoma (1 paper, 2023). The most malignant astrocytic tumor (WHO grade IV). "Consequently, our results strongly indicated that Siglec15 expression was high in M2-like macrophages within the glioblastoma tumor microenvironment." (PMID 37325664, 2023).
leukemia (1 paper, 2023). A malignant (clonal) hematologic disorder, involving hematopoietic stem cells and characterized by the presence of primitive or atypical myeloid or lymphoid cells in the bone marrow and the blood. "Knockdown and knockout of Siglec15 in a murine model of B-ALL was used to evaluate the effect of leukemia-derived Sig15 on the immune response to leukemia." (PMID 37465593, 2023). "In previous work, we noted differential expression of Siglec15 (Sig15) in an immunogenic mouse model of B-ALL as compared with the non-immunogenic control leukemia." (PMID 37465593, 2023).
lymphoma (1 paper, 2022). A malignant (clonal) proliferation of B- lymphocytes or T- lymphocytes which involves the lymph nodes, bone marrow and/or extranodal sites. "That article did not mention the relationship between the expression level of SIGLEC15 and the survival of lymphoma patients." (PMID 36249005, 2022). "Through our survival analysis and experiments, we found that SIGLEC15 is lowly expressed in EBV+ lymphoma patients and can lead to poor prognosis or even death in patients." (PMID 36249005, 2022). "We reported that down-regulation of CHIT1, SIGLEC15, PLA2G2D and TMEM163 was associated with poor prognosis in immunocompetent NHL, and expression levels of four genes were lower in lymphoma than in normal tissues." (PMID 36249005, 2022). "Four differential genes between EBV+ and EBV- lymphoma patients were screened out with the significance of the survival and prognosis of lymphoma, including CHIT1, SIGLEC15, PLA2G2D and TMEM163." (PMID 36249005, 2022). "The role of M0, M2 macrophages in tumor immune microenvironment is consistent with the favorable genes of CHIT1, SIGLEC15, PLA2G2D and TMEM163 for the prognosis of lymphoma patients." (PMID 36249005, 2022).
osteoporosis (1 paper, 2023). A condition of reduced bone mass, with decreased cortical thickness and a decrease in the number and size of the trabeculae of cancellous bone (but normal chemical composition), resulting in increased fracture incidence. "This study is the first to demonstrate that a Siglec‐15 Ab is effective at mitigating bone loss in immobilizing conditions, which includes not only after SCI but should also extend to other disuse conditions that result in severe osteoporosis." (PMID 38130761, 2023).
tumor (61 papers, 2010 to 2026). "A previous study has demonstrated that SIGLEC15, when expressed on tumor-associated macrophages (TAMs), exhibits an M2-like phenotype." (PMID 41158758, 2026). "Specifically, SIGLEC15 is implicated in the inhibition of T cell activity while concurrently mitigating tumor cell metastasis in BRCA." (PMID 41158758, 2026). "Siglec15 was negatively related to the infiltration levels of tumor-associated macrophages in multiple immune cell estimation algorithms, such as TIMER and CIBERSORT." (PMID 33537076, 2021). "Furthermore, SIGLEC15 encodes Siglec-15, which is predominantly expressed in macrophages, osteoclasts, and select tumor cells." (PMID 40507905, 2025). "In addition, high Siglec15 expression was related to M2 tumor-associated macrophages (TAMs), N2 tumor-infiltrating neutrophils, suppressive tumor immune microenvironment, and multiple immune checkpoint molecules." (PMID 37325664, 2023). "This revealed that as SIGLEC15 expression increases, the number of M0 and M1 macrophages decrease, while dendritic cells increase, indicating enhanced anti-tumor immune surveillance." (PMID 41158758, 2026). "Previous studies have demonstrated that higher SIGLEC15 expression in macrophages inhibits T cell activity and promotes the accumulation of M2 pro-tumor macrophages." (PMID 41158758, 2026). "These vesicles also upregulated immune checkpoint molecules, including PD-L1, PD-L2, and SIGLEC-15, contributing to an immunosuppressive tumor microenvironment." (PMID 40924302, 2025). "Several transcripts associated with immunological checkpoints, such as SIGLEC15, PDCD1LG2 (PD-L2), TIGIT, PDCD1 (PD-1), CD274 (PD-L1), CTLA4, LAG3, and HAVCR2 (TIM3), play a crucial role in tumor immune evasion." (PMID 40893939, 2025). "In addition, another immunosuppressive molecule expressed in TCSCs, SIGLEC15, a member of the salivary acid-binding immunoglobulin-like lectin family gene family, modulates various immune cell-mediated immune responses, such as tumor-associated macrophages, CD8 T-cells, NK cells, and MDSCs." (PMID 39776907, 2024). "In our previous study, a novel Siglec‐15 antibody was prepared and showed encouraging tumor‐inhibitory effectiveness in LUAD by modulating macrophage polarization, suggesting a detrimental factor of Siglec‐15 role in cancer management." (PMID 38725348, 2024). "TCSCs overexpress a variety of immunosuppressive molecules such as PD-L1, SIGLEC15, and others to evade immune attack, so blocking suppressive immune checkpoints will reactivate or restore the killing function of anti-tumor-specific immune cells." (PMID 39776907, 2024). "Recent research has found that Siglec15 is also broadly upregulated in human tumor area and tumor infiltrating myeloid cells, and its expression is mutually exclusive to PD-L1." (PMID 37859817, 2023). "Siglec15 is considered a novel anti-tumor target comparable to PD-L1, and has the ability to sustainably suppress T-cell responses and elicit immune evasion in the tumor microenvironment." (PMID 37859817, 2023). "Our findings highlighted the potential functions of Siglec15 in tumor immunity and ECM remodelling, allowing us to revisit its biological role in subsequent analyses." (PMID 37325664, 2023). "Here, we evaluated the relationship between Siglec15 expression (in the stromal area (SA), tumor area (TA) or whole cells), clinicopathological characteristics, and the immune microenvironment in patients with COAD." (PMID 37859817, 2023). "Another study has confirmed that blocking Siglec15 by monoclonal antibody can inhibit tumor growth in mice to a certain extent." (PMID 37256178, 2023). "There was a broad upregulation of Siglec15 in many human cancer cells and tumor-infiltrating immune cells." (PMID 37256178, 2023). "Considering Siglec15 is expressed in tumor cells and tumor infiltrating myeloid cells, we detected Siglec15 in SA, TA and whole cells." (PMID 37859817, 2023).